SOX10 (SRY-box transcription factor 10)
Diseases named in the same sentence as SOX10 in open-access papers (continued):
Sharing a sentence is not in itself a finding about the gene and the disease.
CNS neoplasms (1 paper, 2021). "We stained all 84 molecularly diagnosed CNS-PNET samples with SOX10 monoclonal antibody and also an enlarged set of 263 high-grade pediatric CNS tumors with various histological/molecular diagnoses." (PMID 33536079, 2021). "Immunohistochemical detection of combined expression of SOX10 and ANKRD55 clearly identifies CNS_NBL discriminating them to other hemispheric CNS neoplasms harboring “PNET-like” microscopic appearance." (PMID 33536079, 2021). "Thus, an immunohistochemistry targeting SOX10 and ANKRD55 discriminates between CNS_NBL and other malignant pediatric CNS neoplasms (sensitivity—100% and specificity 98% for CNS_NBL)." (PMID 33536079, 2021). "Stained samples of other embryonal CNS tumors including ATRT, ETMR, HGNET_BCOR, HGNET_MN1 and HGNET_CIC were also completely negative for SOX10." (PMID 33536079, 2021).
digestive tumors (1 paper, 2014). "SOX10 also suppressed the epithelial to mesenchymal transition (EMT) and stemness properties of digestive tumor cells." (PMID 25301735, 2014).
neurodegenerative disease (1 paper, 2023). A disorder of the central nervous system characterized by gradual and progressive loss of neural tissue and neurologic function. "Multiple bioinformatics predictive analyses indicated that Sox10 is closely related to neurodegenerative diseases." (PMID 37108281, 2023). "However, the role of Sox10 in neurodegenerative disease has never been reported." (PMID 37108281, 2023).
prostate (1 paper, 2012). "The expression levels of SOX7 (IRS: PCa = 4.01 ± 0.160 vs. Benign = 4.79 ± 0.279, p = 0.024) and SOX10 (IRS: PCa = 2.76 ± 0.174 vs. Benign = 4.00 ± 0.424, p = 0.010) in PCa tissues were lower than those in adjacent benign prostate tissues significantly." (PMID 22703285, 2012).
tumors of the nervous system (1 paper, 2015). "Dysregulation of SOX10 was reported to be correlated with the progression of multiple cancer types, including melanocytic tumors and tumors of the nervous system." (PMID 26461473, 2015).
vascular disorder (1 paper, 2024). A general term used to describe any disease affecting blood vessels]. "The interaction of G protein signaling regulator 5 with AKT blocks the PI3K / AKT signaling and the phosphorylation at S24 of Sox10, underscoring Sox10 as a potential target in inflammation-related vascular disorders." (PMID 39010066, 2024).
SOX10 also shares sentences with these, for which no sentence is quoted: Anosmia (5 papers); Hearing impairment (4); hypogonadotropic hypogonadism (4); meningioma (4); oligodendroglioma (4); leiomyosarcoma (3); mesothelioma (3); ptosis (3); Waardenburg syndrome type 4C (3); acute myeloid leukemia (2); angiosarcoma (2); bipolar disorder (2); CHARGE syndrome (2); clear cell carcinoma (2); conjunctival melanoma (2); cylindroma (2); Ewing sarcoma (2); fibroma (2); gastric adenocarcinoma (2); glioneuronal tumors (2); leiomyoma (2); malignant glioma (2); neurodevelopmental disorder (2); nodular fasciitis (2); Obesity (2); salivary gland neoplasm (2); soft tissue sarcoma (2); spina bifida (2); actinic keratosis (1); adnexal carcinomas (1).
A further 116 diseases each share a sentence with SOX10 in 1 paper.